LRRC39 (leucine rich repeat containing 39)
Description:
Component of the sarcomeric M-band which plays a role in myocyte response to biomechanical stress. May regulate expression of other M-band proteins via an SRF-dependent pathway. Important for normal contractile function in heart.
Synonyms: Myomasp; MGC14816
Tractability: No criterion of Open Targets' tractability assessment is met for any kind of drug.
Gene: Protein-coding gene on chromosome 1 (100,148,424 to 100,178,267, reverse strand). Ensembl gene ENSG00000122477.
Subcellular location: Cytoplasm, myofibril, sarcomere, M line
Gene Ontology:
Molecular function: protein binding
Biological process: intracellular signal transduction
Cellular component: M band
Genetic constraint (gnomAD): Loss-of-function variants: 32 observed, 35.47 expected, observed/expected ratio (o/e) 0.9, 90% interval 0.68 to 1.21. The upper end of that interval is the gene's LOEUF score, 1.21, which puts it in group 5 of 6, group 1 being the genes least tolerant of losing a copy. Missense variants: 343 observed, 385.19 expected, observed/expected ratio (o/e) 0.89, 90% interval 0.81 to 0.97. Synonymous variants: 111 observed, 136.02 expected, observed/expected ratio (o/e) 0.82, 90% interval 0.7 to 0.95.
Homologues: Orthologues: chimpanzee LRRC39 (95% identical), macaque LRRC39 (93% identical), dog LRRC39 (93% identical), guinea pig LRRC39 (92% identical), rabbit LRRC39 (88% identical), pig LRRC39 (86% identical), mouse Lrrc39 (85% identical), rat Lrrc39 (85% identical), zebrafish lrrc39 (60% identical), tropical clawed frog lrrc39 (56% identical). Paralogues in human: LRRC2 (33% identical), SCRIB (26% identical), LRRC7 (25% identical), ERBIN (25% identical), LRRC1 (24% identical), SHOC2 (24% identical), LRRIQ4 (24% identical), LRRC8A (24% identical), LRRC40 (24% identical), LRRC8C (23% identical), LRRC8D (23% identical), LRRC8E (23% identical), and 19 more.
Diseases named in the same sentence as LRRC39 in open-access papers:
LRRC39 is named in the same sentence as 5 diseases in open-access papers, as found by Europe PMC text mining. Sharing a sentence is not in itself a finding about the gene and the disease. The quoted sentences say what the papers report.
retinoblastoma (2 papers, 2021 to 2024). A malignant tumor that originates in the nuclear layer of the retina. "It has been reported that CLUL1, CNGB1, ROM1, LRRC39, and RDH12 genes in different retinoblastoma subtypes are involved in the progression and development of the disease, which can be useful as biomarkers (M.)." (PMID 34646884, 2021).
behavioral disorders (1 paper, 2025). "Notably, genes associated with immune modulation and inflammation (e.g., Dusp1, Lrrc39, E2f2), neuroplasticity and memory (e.g., Cpeb3, Efnb3), and behavioral disorders (e.g., Pla2g4c) exhibited substantial changes." (PMID 40285614, 2025).
pulmonary fibrosis (1 paper, 2022). Chronic progressive interstitial lung disorder characterized by the replacement of the lung tissue by connective tissue, leading to progressive dyspnea, respiratory failure, or right heart failure. "Thus, there is already evidence that IL7R, LBH, and CXCR6 are important for understanding processes that promote pulmonary fibrosis, and LRRC39 and PLBD1 are additional targets for future studies." (PMID 35715807, 2022). "Five genes demonstrated concordant directions of effects between the ILA [IPF transcripts] and IPF scores (CXCR6, IL7R, LBH, LRRC39, PLBD1), suggesting these genes may represent important biologic processes in promoting the progression of pulmonary fibrosis." (PMID 35715807, 2022).
LRRC39 also shares sentences with these, for which no sentence is quoted: cardiomyopathy (1 paper); clear cell renal cell carcinoma (1).